SPAG16 (sperm associated antigen 16)
Description:
Necessary for sperm flagellar function. Plays a role in motile ciliogenesis. May help to recruit STK36 to the cilium or apical surface of the cell to initiate subsequent steps of construction of the central pair apparatus of motile cilia (By similarity).
Synonyms: PF20; FLJ22724; DKFZp666P1710; WDR29
Tractability: Antibody: its Gene Ontology location is reachable by antibodies, with medium confidence; the Human Protein Atlas places it where antibodies can reach. PROTAC: ubiquitination databases record sites on it.
Gene: Protein-coding gene on chromosome 2 (213,284,389 to 214,410,501, forward strand). Ensembl gene ENSG00000144451.
Subcellular location: Cytoplasm; Cytoplasm, cytoskeleton, flagellum axoneme; Cytoplasm, cytoskeleton, cilium axoneme; Cell projection, cilium, flagellum
Subcellular location (Human Protein Atlas): Cytosol; Equatorial segment; Acrosome; Plasma membrane; Vesicles
Gene Ontology:
Biological process: axoneme assembly; cilium assembly
Cellular component: axonemal central apparatus; axoneme; cytoplasm; motile cilium; sperm flagellum
Genetic constraint (gnomAD): Loss-of-function variants: 40 observed, 41.3 expected, observed/expected ratio (o/e) 0.97, 90% interval 0.75 to 1.26. The upper end of that interval is the gene's LOEUF score, 1.26, which puts it in group 5 of 6, group 1 being the genes least tolerant of losing a copy. Missense variants: 515 observed, 466.22 expected, observed/expected ratio (o/e) 1.1, 90% interval 1.03 to 1.19. Synonymous variants: 191 observed, 177.33 expected, observed/expected ratio (o/e) 1.08, 90% interval 0.96 to 1.21.
Homologues: Orthologues: chimpanzee SPAG16 (99% identical), macaque SPAG16 (96% identical), dog SPAG16 (86% identical), pig SPAG16 (85% identical), rabbit SPAG16 (79% identical), mouse Spag16 (75% identical), tropical clawed frog spag16 (52% identical), rat Spag16 (41% identical).
Diseases named in the same sentence as SPAG16 in open-access papers:
SPAG16 is named in the same sentence as 24 diseases in open-access papers, as found by Europe PMC text mining. Sharing a sentence is not in itself a finding about the gene and the disease. The quoted sentences say what the papers report.
multiple sclerosis (4 papers, 2017 to 2025). A progressive autoimmune disorder affecting the central nervous system resulting in demyelination. "Although traditionally associated with ciliary structure, SPAG16 has also been recognized as a target of humoral immune responses in multiple sclerosis (MS)." (PMID 40724541, 2025). "The cilia-related SPAG16 gene has been associated to rheumatoid arthritis, possibly via extracellular matrix degradation, and a subgroup of multiple sclerosis patients express SPAG16 autoantibodies that intensify symptoms in a mouse model of the disease." (PMID 39165421, 2024). "Previous studies have shown that SPAG16 is associated with osteoporosis, primary ciliary motility disorder (PCD), multiple sclerosis, and reduced male fertility due to arsenism and fluorosis." (PMID 36213906, 2022).
infertile (3 papers, 2012 to 2017). "The present study analyzed genetic variation in a population of infertile males, and their association with parameters that are potentially regulated by SPAG16." (PMID 22963137, 2012). "A deficiency in SPAG16 is associated with infertility in male mice due to impaired sperm motility." (PMID 28659810, 2017). "In the present study, we analyzed DNA samples from 60 infertile male volunteers of Western European (Italian) origin, to search for novel SPAG16 gene mutations, and to determine whether increased prevalence of SPAG16 single nucleotide polymorphisms (SNPs) was associated with infertility phenotypes." (PMID 22963137, 2012).
male infertility (3 papers, 2011 to 2025). The inability of the male to effect fertilization of an ovum after a specified period of unprotected intercourse. "In mice, we have previously shown that loss of Spag16 gene function causes male infertility and severe sperm motility defects." (PMID 22963137, 2012). "While homozygosity for a SPAG16L-deletion mutation produced male infertility, the mutant allele was transmitted in the chimeric and heterozygous states, and the perturbation of spermatogenesis observed with total SPAG16 knockout was not seen." (PMID 21655194, 2011).
bronchiectasis (1 paper, 2021). Segmental, irreversible dilation of the bronchial tree resulting in the accumulation of secretions which leads to obstruction. "Homozygous pathogenic genetic variant in the SPAG16 (c.1067G > A) gene was detected for the first time in our study in a male patient with ciliary dyskinesia, slowly motile airway cilia, bronchiectasis, and sinusitis." (PMID 34445527, 2021).
cancer-testis (1 paper, 2023). "The Sperm Associated Antigen 16 (SPAG16) is one of the cancer-testis (CT) antigens which are significantly associated with activation of the anticancer immune response." (PMID 37310469, 2023).
hypospadias (1 paper, 2018). Hypospadias is the displacement of the urethral meatus on the ventrum of the penis. "Finally, three other deletions were found respectively in SPAG16, playing a role in the axoneme of the sperm, RYR2, whose mutations have been associated to cardiac diseases and ATF3, a candidate gene for hypospadias." (PMID 30042735, 2018).
leukemia (1 paper, 2023). A malignant (clonal) hematologic disorder, involving hematopoietic stem cells and characterized by the presence of primitive or atypical myeloid or lymphoid cells in the bone marrow and the blood. "The rs77756144 lies in-between the gene IKZF2 and SPAG16, among which the IKZF2 appears to be a probable candidate targeted for selection given its involvement in HTLV-1 infection related leukemia." (PMID 37903429, 2023).
neuroblastoma (1 paper, 2018). Neuroblastoma (NB) is the most common solid, extracranial childhood tumor. "This analysis identified a novel variant in SPAG16 that is significantly more common in African American children who developed high-risk neuroblastoma and rarely present in Caucasians." (PMID 30200332, 2018).
prostate carcinoma (1 paper, 2023). A carcinoma that arises from epithelial cells of the prostate gland. "Genes that are of high importance in our RF models that are associated with both LCC and prostate cancer include PRAC1, HOXB13, SPAG16." (PMID 37434131, 2023).
psychosomatic disorders (1 paper, 2022). "Besides, we found that rs9677504 (SPAG16 locus) affects the severity of psychosomatic disorders and abstract thinking ability." (PMID 36213906, 2022).
tumor (4 papers, 2017 to 2022). "CQ-PCR also showed copy number variation of EGFR, normalized to the reference gene SPAG16, in the original tumor and derived cultures at various passages." (PMID 29113349, 2017). "One mouse with two doses of ZR30 treatment showed no sign of weight loss and CQ-PCR of the entire right hemisphere showed human SPAG16 / mouse Spag16 gene copy ratio = 0.03, suggesting successful cell implantation and ZR30-mediated suppression of tumor formation from both i.t. treatments." (PMID 29290950, 2017).
cancer (3 papers, 2022 to 2023). A tumor composed of atypical neoplastic, often pleomorphic cells that invade other tissues. "In a previous study, SPAG16 was upregulated in a variety of cancer tissues and may therefore serve as a potential target for immunotherapy." (PMID 37310469, 2023).
SPAG16 also shares sentences with these, for which no sentence is quoted: rheumatoid arthritis (2 papers); cardiac diseases (1); cataract (1); ciliary dyskinesia (1); fluorosis (1); Hydrocephalus (1); Hypertension (1); lung carcinoma (1); melanoma (1); Obesity (1); osteoporosis (1); sinusitis (1).